CYP1B1 (cytochrome P450 family 1 subfamily B member 1)
Diseases named in the same sentence as CYP1B1 in open-access papers (continued):
Sharing a sentence is not in itself a finding about the gene and the disease.
COVID-19 (3 papers, 2021 to 2023). A disease caused by infection with severe acute respiratory syndrome coronavirus 2. "Our study shows for the first time that Wnt5A induces the gene expression of CYP1A1 and CYP1B1 enzymes involved in phase I metabolism of a broad spectrum of drugs including chloroquine (the controversial drug for COVID-19) that is known to cause toxicity in myocardium." (PMID 34079452, 2021). "During hyperoxic conditions, as occurring in COVID-19, CY1B1, whose production is enhanced by TNF-α, buffers ROS by forming oxidized adducts in DNA; therefore, COVID-19 is a condition where the role of CYP1B1 as a key regulator of ROS as signaling molecules is impaired, due to TNF-α." (PMID 36140358, 2022).
hepatoma (3 papers, 2015 to 2021). "Moreover, when hepatoma cells (SK-Hep1) were treated with TCDD, a prototypical AHR ligand, expressions of HDAC8 and the classical AHR target gene CYP1B1 were increased in hepatoma cells in a time-dependent manner, both at protein level." (PMID 27283490, 2017). "Forced AHR overexpression enhanced mRNA and protein expression of CYP1B1 and HDAC8 in both hepatoma cell lines." (PMID 27283490, 2017). "By using a cutoff value of β > 0.5, we identified five DME genes (CYP1B1, CYP8B1, GSTM2, GSTP1, and UGT3A2) that were regulated by DNA methylation in hepatoma cells." (PMID 26421064, 2015). "Among these DME genes, the downregulation of CYP1B1, CYP8B1, GSTM2, GSTP1, UGT2B15, and UGT3A2 in hepatoma cells could be explained by DNA methylation status." (PMID 26421064, 2015). "We also provided experimental evidence to support the interaction between rutaecarpine and AhR in mouse hepatoma cells using the well-established DRE-driven reporter gene assay, as well as in human glioblastoma cells via determination of the classical AhR responsive gene CYP1B1." (PMID 34955744, 2021).
Hyperglycemia (3 papers, 2019 to 2025). An increased concentration of glucose in the blood. "The blockage of CYP1B1 inhibits EVT activities induced by hyperglycemia in vitro, including proliferation, migration, and invasion, whereas the exogenous expression of CYP1B1 exhibits the opposite effects." (PMID 35515562, 2019). "On the other hand, inflammation secondary to hyperglycemia may downregulate some drug-metabolizing CYPs, while upregulating others like CYP1B1, indicating a complex regulation by metabolic stress and ROS." (PMID 40621132, 2025).
kidney cancer (3 papers, 2015 to 2025). Primary or metastatic malignant neoplasm involving the kidney. "In conclusion, our results demonstrate that ADAM12 and CYP1B1 are highly expressed in CAAs of kidney cancer and that their expression linearly follows the body weight." (PMID 39806854, 2025). "Therefore, it would be of great interest to determine whether miR-27b-mediated CYP1B1 regulation is involved in docetaxel resistance in both breast and kidney cancers." (PMID 25860934, 2015). "We observed that ADAM12 and CYP1B1 downregulation has a deep impact on the proliferative ability and the invasiveness of RCC cells, pointing to a critical role of these genes in regulating tumor–stroma interplay and fostering kidney cancer in obese patients." (PMID 39806854, 2025).
liver cancer (3 papers, 2021 to 2022). An epithelial or non-epithelial malignant neoplasm that arises from the liver. "Furthermore, the downregulation of ZNF165 could significantly decrease the expression of AhR, CYP1A1, and CYP1B1 in liver cancer cells." (PMID 35692498, 2022).
lung diseases (3 papers, 2014 to 2023). "The role of MMP12, SPP1, AHRR and CYP1B1 in cigarette smoke-related lung diseases have been well described and studied." (PMID 24663285, 2014). "KEGG analysis suggested that metabolism of xenobiotics by cytochrome P450 (CYP1B1, CYP1A1 and ALDH3A1), an important signalling pathway that influences the xenobiotic metabolizing capability of the lung and the risk of developing of lung diseases, was associated with COPD." (PMID 32961012, 2020).
neuroblastoma (3 papers, 2021 to 2024). Neuroblastoma (NB) is the most common solid, extracranial childhood tumor. "Mn exposure reduced mRNA levels of CYP1B1 in both endothelial hCMEC/D3 cells and neuroblastoma SH‐SY5Y cells." (PMID 38429921, 2024). "Using targeted transcriptomic analysis and qPCR, we observed a significant increase in the expression of genes related to the AHR pathway (CYP1A1, CYP1B1, AHRR) in mouse OPCs and human neuroblastoma SH-SY5Y cells after treatment with EDA." (PMID 38672460, 2024).
ocular hypertension (3 papers, 2013 to 2024). Abnormally high intraocular pressure. "Based upon these considerations, we started a study for identifying myocilin (MYOC) and cytochrome P450, family 1, subfamily B, polypeptide 1 (CYP1B1) mutations in a Spanish population with different clinical forms of familial glaucoma or ocular hypertension (OHT)." (PMID 23922489, 2013). "Further, various reports indicated ocular hypertension in Cyp1b1-/- mice induced by increased levels of oxidative stress, corresponding to the changes seen in human glaucomatous TM tissues, suggesting the role of CYP1B1 in the suppression of oxidative stress." (PMID 38755526, 2024).
Parkinson disease (3 papers, 2012 to 2025). A progressive degenerative disorder of the central nervous system characterized by loss of dopamine producing neurons in the substantia nigra and the presence of Lewy bodies in the substantia nigra and locus coeruleus. "Dementia-related genes ARHGAP27, CYP1B1, KANSL1, KRTCAP2, LSM7, and GBA are also linked to altered behavior, neurodegeneration, inflammation, and Parkinson’s." (PMID 37588516, 2023). "For example, if “Parkinson's disease” is entered, the list of validated miRNAs and targets returned are: has-miR-1:BDNF; has-miR-27b:CYP1B1; has-miR-433:FGF20; miR-124:CYP1B1; has-miR-1:GCH1; has-miR125b:CYP1A1." (PMID 23316214, 2012).
thyroid cancer (3 papers, 2020 to 2025). "To investigate if AhR overexpression in thyroid cancers was associated with the activation of its transcriptional activity, we evaluated the expression levels of AhR target gene CYP1B1." (PMID 31936153, 2020). "In thyroid-tumor samples, the AhR target genes CYP1A1 and CYP1B1 were upregulated relative to associated healthy tissue and again Kyn stimulation of thyroid-cancer cell lines promoted the acquisition of an EMT program (decreased E-cadherin, and increased SLUG, N-cadherin, and fibronectin levels)." (PMID 33451095, 2021). "After having evaluated expression and activation state of AhR in human thyroid cancer samples, we analyzed AhR and CYP1B1 expression in human thyroid carcinoma cell lines." (PMID 31936153, 2020). "AhR mRNA expression resulted significantly higher in all the analyzed thyroid cancer samples compared to normal thyroid and a statistically significant correlation with CYP1B1 was detected." (PMID 31936153, 2020). "The level of AhR functional activation was evaluated by measuring CYP1A1 and CYP1B1 mRNA expression in the thyroid cancer samples." (PMID 31936153, 2020). "Furthermore, prognostic ROC curves based on the GEO validation set demonstrated that CYP1B1, GABRB2, and TNFSF15 were significantly associated with thyroid cancer diagnosis (AUC exceeding 0.86)." (PMID 40900788, 2025). "Through computational network toxicology analysis, this study identifies CYP1B1, GABRB2, and TNFSF15 as potential molecular targets mediating DEHP’s effects in thyroid cancer." (PMID 40900788, 2025). "CYP1B1, GABRB2, and TNFSF15 have been identified as significant target genes that can collectively predict the prognosis of thyroid cancer and possess high clinical value." (PMID 40900788, 2025).
age-related macular degeneration (2 papers, 2020 to 2022). Age-related loss of vision in the central portion of the retina (macula), secondary to retinal degeneration. "Up-regulates AhR target genes CYP1A1 and CYP1B1 and may prevent age-related macular degeneration." (PMID 35566359, 2022).
Alzheimer disease (2 papers, 2024 to 2025). A progressive, neurodegenerative disease characterized by loss of function and death of nerve cells in several areas of the brain leading to loss of cognitive function such as memory and language. "These analyses confirmed an inverse correlation between CYP1B1 and miR-200c, suggesting that this relationship could provide a viable strategy for diagnosing and treating degenerative diseases such as Alzheimer's disease." (PMID 39812050, 2025).
aneurysm (2 papers, 2018 to 2025). Bulging or ballooning in an area of an artery secondary to arterial wall weakening. "Vascular site-specific expression of Cyp1b1 is particularly notable as it contributes to abdominal aortic aneurysm and suggests a vascular site-specific mechanism of aneurysm." (PMID 40931195, 2025).
autism (2 papers, 2021 to 2025). Persistent deficits in social interaction and communication and interaction as well as a markedly restricted repertoire of activity and interest as well as repetitive patterns of behavior. "El-Ansary and colleagues investigated the connection between CYP1B1-mediated vitamin D deficiency and autism and reported that plasma levels of CYP1B1 and vitamin D were 70% lower in children with autism than in age- and sex-matched neurotypical children." (PMID 39812050, 2025). "The link between CYP1B1-mediated vitamin D deficiency and autism has been examined by El-Ansary and coworkers, who were the first to show that the plasma levels of CYP1B1 and vitamin D in 28 children with autism were 70% lower than their age- and sex-matched neurotypical children." (PMID 34502168, 2021). "What supports this possibility is that AhR and its regulated genes, CYP1A1, CYP1A2, and CYP1B1, are highly and constitutively expressed in the placenta, which may be activated by exposure to environmental toxicants during pregnancy and, hence, increase the incidence of autism." (PMID 34502168, 2021). "This section summarizes the most recent human and experimental studies and evidence for the potential role of AhR and its regulated genes, CYP1A1, CYP1B1, and CYP1A2 on autism development." (PMID 34502168, 2021).
bladder urothelial carcinoma (2 papers, 2020 to 2023). "Regarding CYP1B1 significance at the tumor level, CYP1B1 was associated both with protective overall survival in skin cutaneous melanoma and sarcoma, whereas its expression correlates with tumor stage in bladder urothelial carcinoma and other tumors." (PMID 37371125, 2023). "Low expression of CYP1B1 in cancer corresponded to better survival detected by Kaplan-meier plot for kidney (renal) clear cell carcinoma and bladder urothelial carcinoma with p-value 0.00265 and 0.0175 respectively." (PMID 32626511, 2020). "We have promising disease candidates for CYP1B1 inhibitor trials which are kidney renal clear cell carcinoma and bladder urothelial carcinoma." (PMID 32626511, 2020).
endometriosis (2 papers, 2012 to 2023). The growth of functional endometrial tissue in anatomic sites outside the uterine body. "Endometriosis risk is also correlated with CYP1B1 SNPs, which increases the backward conversion of melatonin to NAS." (PMID 37600687, 2023). "Several SNPs of the estrogen synthesis- and metabolism-related genes, such as CYP19, CYP1A1 and COMT, and CYP1B1, have been found to be associated with increased risk of endometriosis." (PMID 23139742, 2012).
fibrosis (2 papers, 2020 to 2025). the formation of excess fibrous connective tissue in an organ or tissue in a reparative or reactive process. "CYP1B1 has also been shown to induce EMT which is involved in cardiac fibrosis and in cancer progression." (PMID 33185690, 2020).
glioblastoma (2 papers, 2021 to 2024). The most malignant astrocytic tumor (WHO grade IV). "Our investigation revealed an upregulation of CYP1B1 in samples of glioblastoma multiforme (GBM)." (PMID 38214842, 2024).
hyperandrogenism (2 papers, 2022 to 2023). Excessive secretion of androgens from the adrenal glands or gonads. "In women with PCOS, a correlation between elevated levels of AhR, ARNT, CYP1A1, and CYP1B1 genes and clinical hyperandrogenism, follicular fluid testosterone levels, and disturbed folliculogenesis was observed." (PMID 37572199, 2023). "The results of our study showed that in PCOS patients, the significant positive correlations were obtained for Ahr, Arnt, Cyp1A1, and Cyp1B1 with incidence of clinical hyperandrogenism." (PMID 36368943, 2022). "Also, the significant positive correlations were obtained for Ahr, Arnt, Cyp1A1, and Cyp1B1 with incidence of clinical hyperandrogenism and FFT level." (PMID 36368943, 2022). "Moreover, we showed that there is a correlation between clinical hyperandrogenism and follicular testosterone levels and Cyp1A1, and Cyp1B1 mRNA levels." (PMID 36368943, 2022).
inflammatory breast carcinoma (2 papers, 2019 to 2022). An advanced, invasive breast adenocarcinoma characterized by the presence of distinct changes in the overlying skin. "Over-expression of CYP1B1 has been shown to correlate with Wnt5/6-β-catenin signaling, stem cell phenotype and poor clinical prognostic factors in inflammatory breast cancer." (PMID 32047513, 2019). "In inflammatory breast cancer, the CD44+/CD24−/low cancer stem cell subset harbors higher levels of CYP1B1, and 4-OHE2 treatment induces anchorage-independent growth of mammary epithelial cells." (PMID 35292057, 2022).
ischemia (2 papers, 2022). A hypoperfusion of the BLOOD through an organ or tissue caused by a PATHOLOGIC CONSTRICTION or obstruction of its BLOOD VESSELS, or an absence of BLOOD CIRCULATION. "We found that endothelial markers (Angptl4), and pericyte marker (Cyp1b1, Emp1, S1pr3, Serping1, and Cxcl1) were upregulated in prolonged ischemia." (PMID 35154109, 2022). "Nonetheless, effects of this altered input may differ regarding CYP1B1 expression, as CA2 possesses an innate resistance to ischemia and TBI relative to other subregions." (PMID 35054909, 2022).
laryngeal carcinoma (2 papers, 2014 to 2016). Carcinoma that arises from the laryngeal epithelium. "Smoking and drinking showed collaborative effects with two high risk alleles (CYP1B1*2 355T and CYP1B1*3 4326G) for promoting laryngeal cancer risk." (PMID 25299224, 2014). "CYP1B1*2 355T and CYP2E1*5 -1293C are associated with an increased laryngeal cancer risk, while CYP1B1*3 4326G is associated with a decreased risk." (PMID 25299224, 2014). "In our study, mutation allele CYP1B1 4326G was associated with a decreased risk for laryngeal cancer." (PMID 25299224, 2014). "The mutant allele CYP1B1*2 4326G shows a protective effect against developing laryngeal cancer (P <0.001)." (PMID 25299224, 2014). "In contrast, individuals with the CG or GG genotype at the CYP1B1*3 C4326G locus showed a significantly lower risk for developing laryngeal cancer compared to individuals with the CC genotype (crude OR = 0.545, 95% CI: 0.407–0.729, P <0.001)." (PMID 25299224, 2014). "Mutation allele (CYP1B1*2 355T) may also increase the risk for laryngeal cancer, possibly due to the increased catalytic activity for 17β-oestradiol 4-hydroxylation contributed by that mutation." (PMID 25299224, 2014). "In our study, we found that among individuals with a history of similar environmental exposures, those individuals carrying the CYP1B1*2 355T allele (genotype GT+TT) showed a significantly increased risk for laryngeal cancer compared to individuals with the wild type gene (GG)." (PMID 25299224, 2014). "Similarly, both smoking and drinking showed a collaborative effect for increasing the risk of laryngeal cancer in patients with the wild type allele 4326C at the CYP1B1*3 C4326G locus." (PMID 25299224, 2014). "This study was conducted to explore the effects of genetic polymorphisms (CYP1B1*2 G355T, CYP1B1*3 C4326G, and CYP2E1*5 G-1293C) and environmental factors (smoking and drinking) on susceptibility to laryngeal cancer in a Han Chinese study group." (PMID 25299224, 2014). "Haplotype G355G4326G−1293 was associated with a lower laryngeal cancer risk than haplotype G355C4326G−1293, which is consistent with the protective effect of the CYP1B1*3 4326G allele, and also suggested an additive genetic effect among these alleles." (PMID 25299224, 2014). "Environmental factors (smoking and drinking) and genetic factors (CYP1B1*2 355T and CYP2E1*5 -1293C) are both associated with an individual's susceptibility to developing laryngeal cancer (P value for all these evaluations were < 0.001)." (PMID 25299224, 2014). "In summary, our case-control study showed that genetic polymorphisms of CYP1B1 and CYP2E1 are closely associated with an individual's susceptibility to developing laryngeal cancer." (PMID 25299224, 2014). "Our case-control study of the Han Chinese population revealed that three SNPs at CYP1B1*2 G355T, CYP1B1*2 C4326G, and CYP2E1*5 G-1293C are associated with an individual's susceptibility to laryngeal cancer." (PMID 25299224, 2014). "Here, we report results of a case-control study investigating the association of three important SNPs of P450 (CYP1B1*2 G355T, CYP1B1*3 C4326G, and CYP2E1*5 G-1293C) and two major environmental factors (smoking and drinking) with susceptibility to laryngeal cancer." (PMID 25299224, 2014).
leukaemia (2 papers, 2015 to 2023). "The expression of CYP1B1 is reported to be elevated in various malignancies, however, its expression is downregulated in early age leukaemia, as seen in our cohort." (PMID 36845715, 2023). "Regarding CYP1B1 and leukemia subtype, higher levels of gene expression were detected in girls with ALL and in boys with AML." (PMID 25992585, 2015). "CYP1B1 was not expressed in 57.1% of EAL cases, and its expression varied by genotype, gender, and leukemia subtype." (PMID 25992585, 2015).
meningioma (2 papers, 2015 to 2023). A generally slow growing tumor attached to the dura mater. "In our study, meningiomas exhibited twenty-two times higher CYP1B1 mRNA expression than the average expression of all other tumors." (PMID 26580399, 2015). "The exposure of the meningioma cell lines to chemically induced hypoxia increased the level of AhR mRNA ninefold as compared with the control cultured cells but did not alter the mRNA level of ARNT and of an AhR target gene (CYP1B1)." (PMID 37305351, 2023).
metastatic disease (2 papers, 2004 to 2013). "We have recently shown that CYP1B1 demonstrates a similarly high level of expression in metastatic disease." (PMID 15280921, 2004).
microphthalmia (2 papers, 2017 to 2021). Congenital or developmental anomaly in which the eyeballs are abnormally small. "Further, the increase in RA as a result of cyp1b1 overexpression decreased the microphthalmia induced through RA deficiency (Raldh2 MO)." (PMID 28192799, 2017). "Clinical sequencing and deletion/duplication analysis of PAX6, FOXC1, PITX2, and CYP1B1, as well as a clinical microphthalmia/anophthalmia gene panel, did not reveal causative variants." (PMID 33973683, 2021).